RFESD (Rieske Fe-S domain containing)
Tractability: No criterion of Open Targets' tractability assessment is met for any kind of drug.
Gene: Protein-coding gene on chromosome 5 (95,646,718 to 95,684,773, forward strand). Ensembl gene ENSG00000175449.
Subcellular location (Human Protein Atlas): Nucleoplasm
Gene Ontology:
Molecular function: protein binding; 2 iron, 2 sulfur cluster binding
Genetic constraint (gnomAD): Loss-of-function variants: 12 observed, 21.25 expected, observed/expected ratio (o/e) 0.56, 90% interval 0.36 to 0.92. The synonymous counts are far from expectation, so gnomAD's model fits this gene poorly and the ratio says little. Missense variants: 182 observed, 226.07 expected, observed/expected ratio (o/e) 0.81, 90% interval 0.71 to 0.91. Synonymous variants: 49 observed, 73.64 expected, observed/expected ratio (o/e) 0.67, 90% interval 0.53 to 0.84.
Homologues: Orthologues: chimpanzee RFESD (99% identical), macaque RFESD (98% identical), dog RFESD (67% identical), pig RFESD (67% identical), guinea pig RFESD (65% identical), mouse Rfesd (65% identical), rabbit RFESD (64% identical), rat Rfesd (61% identical), zebrafish RFESD (37% identical), zebrafish rfesd (29% identical).